SNORA6 (small nucleolar RNA, H/ACA box 6)
Synonyms: ACA6
Gene: Small nucleolar RNA gene on chromosome 3 (39,408,389 to 39,408,539, forward strand). Ensembl gene ENSG00000206760.
Gene Ontology:
Biological process: RNA processing
Cellular component: nucleolus
Homologues: Orthologues: chimpanzee SNORA62 (99% identical), macaque SNORA62 (98% identical), pig SNORA62 (93% identical), mouse Gm24044 (91% identical), chimpanzee SNORA62 (91% identical), rat Snora6 (91% identical), rat LOC120098349 (90% identical), dog SNORA62 (89% identical), rat LOC120102622 (89% identical), guinea pig SNORA6 (83% identical), rat LOC120099439 (72% identical), zebrafish SNORA62 (67% identical), and 3 more. Paralogues in human: SNORA62 (72% identical), SNORA62 (65% identical), SNORA62 (62% identical), SNORA62 (60% identical), SNORA62 (58% identical), SNORA62 (41% identical), SNORA62 (36% identical).
Diseases named in the same sentence as SNORA6 in open-access papers:
SNORA6 is named in the same sentence as 2 diseases in open-access papers, as found by Europe PMC text mining. Sharing a sentence is not in itself a finding about the gene and the disease.
SNORA6 shares sentences with these, for which no sentence is quoted: infarction (1 paper); rheumatoid arthritis (1).